SND1 (staphylococcal nuclease and tudor domain containing 1)
Diseases named in the same sentence as SND1 in open-access papers (continued):
Sharing a sentence is not in itself a finding about the gene and the disease.
breast carcinoma (continued). "A recent study in a breast cancer model demonstrated that SND1 significantly interacts with the promoter regions of several genes in the TGFβ signaling pathway, including Smad 1–4 and TGFβ." (PMID 25405367, 2015). "Previous studies have reported that MTDH interacts with SND1 to promote breast cancer progression." (PMID 40775338, 2025). "We further explored the functional roles of SND1 in HR+/HER2− breast cancer." (PMID 40940685, 2025). "In summary, our study revealed the stimulatory effects of XBP1s on cell proliferation, cell cycle progression from G1 to S phase, and the development of cross‐resistance to palbociclib and fulvestrant by modulating the SND1/E2F1 axis in HR+/HER2− breast cancer." (PMID 40940685, 2025). "Our recent study showed SND1 can induce histone lysine acetylation in breast cancer via GCN5." (PMID 37885030, 2023). "Additional evidence for Snd1 in stress responses has been provided in the context of breast cancer tumorigenesis where Snd1 stabilized the expression of pro‐survival genes under stress conditions through yet unknown mechanism." (PMID 37151849, 2023). "SND1, a component of the RNA-induced silencing complex, is an oncogene involved in tumorigenesis, tumor progression, and metastasis in multiple malignancies, including breast cancer and colorectal cancer." (PMID 36669591, 2023). "Recently, SND1 was reported to play essential roles in breast cancer metastasis; however, whether SND1 localizes to mitochondria and regulates cell proliferation and tumor progression through mitochondrial-related functions is largely unknown." (PMID 35433434, 2022). "peptide that could disrupt the AEG-1–SND1 interaction in vivo, induce SND1 degradation and inhibit the growth of human breast cancer xenografts." (PMID 33918653, 2021). "Hence, reduced SND1 expression in breast cancer cells resulted in decreased invasive and self-renewal capacity and also increased sensitivity to Dox." (PMID 32117742, 2020). "We reported it here that SND1 promotes the invasive and self-renewal capacity of breast cancer cells and increased sensitivity to Dox, which might be afforded by increased expression of SND1 downstream targets, SMAD2/3/4." (PMID 32117742, 2020). "Hence, inhibition of Linc00668 in breast cancer cells suppressed SND1 mediated migration, invasion, self-renewal, and doxorubicin resistance." (PMID 32117742, 2020). "The downstream action of SND1, functioning as a coactivator, finally results in the disruption of cytoskeletal organization and increased cell motility and invasion and metastasis of breast cancer." (PMID 30619748, 2018). "It has been illustrated that overexpression of either miR-361-5p, miR-184, or miR-320a decreased cancer cell viability, migration and invasion through direct downregulation of SND1 oncogene in gastric and colorectal cancer, in malignant glioma and breast cancer and in lung cancer cells." (PMID 30619748, 2018). "There might be a positive regulatory mechanism to maintain levels of c-Myb and SND1 that potentially maintain tumorigenesis in breast cancer." (PMID 25405367, 2015). "In breast cancer, SND1 could interact with MTDH and promoter cancer progression." (PMID 37885030, 2023). "Thus, SND1 is essential for pro-oncogenic properties of AEG-1 in breast cancer." (PMID 25405367, 2015). "C26-A6 works at μM concentrations in vitro, and a new compound C19 was generated which disrupted AEG-1/SND1 interaction at nM concentrations and also inhibited MCF-7 human breast cancer xenografts in nude mice." (PMID 40282551, 2025). "SND1 levels were similar in WT and AEG-1 knocked-down breast cancer cells under steady-state conditions." (PMID 40282551, 2025). "Based on in vivo and in vitro studies, we revealed that XBP1s enhanced the expression of E2F1 target genes by transcriptional activation of SND1, thereby exerting a pro‐survival effect in patients with HR+/HER2− breast cancer receiving the combined therapy." (PMID 40940685, 2025).
breast carcinoma (continued). "Our study observed that the high level expressed SND1 in TNBC cell lines significantly increased the expression of DNMT3A, leading to aberrant methylation patterns of CDH1 and promoting breast cancer metastasis." (PMID 37885030, 2023). "Using a variety of mouse models, a key role of AEG-1 in the expansion of TICs in breast cancer was elucidated, facilitating metastasis, and it was documented that AEG-1 exerted its effect by interacting and stabilizing SND1." (PMID 33918653, 2021). "This review will discuss some recent progresses about the alternative splicing regulators such as CD44, heterogeneous nuclear ribonucleoprotein M (hnRNPM), SND1 and MTDH etc. in breast cancer metastasis." (PMID 31737791, 2019). "In breast cancer, AEG-1 has been shown to promote the expansion of tumor-initiating cells (TICs) facilitating metastasis, and AEG-1/SND1 interaction, followed by stabilization of SND1 protein, was shown to be a key event in this process." (PMID 40282551, 2025). "In addition, interaction of Snd1 with the RNA‐binding protein Metadherin (MTDH) was shown to be critical for early‐stage tumorigenesis in oncogene and carcinogen‐induced mammary tumor models where Snd1 stabilized the expression of pro‐survival genes under stress conditions." (PMID 37151849, 2023).
glioma (18 papers, 2015 to 2025). A benign or malignant brain and spinal cord tumor that arises from glial cells (astrocytes, oligodendrocytes, ependymal cells). "Collectively, our results indicate the interaction relationship between LINC00461 and SND1, and their interaction or association may be perturbed during the progression of glioma, which provides a candidate potential marker for glioma." (PMID 37260771, 2023). "Furthermore, for lncRNA LINC00461, we examined the interaction relationship between LINC00461 and SND1, and the association may be perturbed during the progression of glioma." (PMID 37260771, 2023). "The competitive binding of lncRNA SNAI3-AS1 to SND1 disrupts the m6A-dependent recognition of 3′-UTR in Nrf2 mRNA by SND1, ultimately reducing the mRNA stability of Nrf2 and promoting ferroptosis in gliomas." (PMID 39210921, 2024). "SND1 expression was increased in tumors such as bladder cancer, glioma, and ovarian cancer and correlated with proliferation and metastasis as well as chemoresistance." (PMID 37779184, 2023). "In glioma cells, SND1 can induce a long-range chromatin interaction loop between two SND1 recognition positions on the RHOA promoter." (PMID 37885030, 2023). "We also confirmed that SNAI3-AS1 perturbs the m6A recognition of Nrf2 mRNA 3’UTR by SND1 to decrease Nrf2 mRNA stability, thereby promoting erastin-induced ferroptosis in glioma." (PMID 37202791, 2023). "Epigenetically silenced lncRNA SNAI3-AS1 has been found to promote ferroptosis in glioma by disrupting the m6A-dependent recognition of Nrf2 mRNA through SND1." (PMID 37723588, 2023). "We also observed a significant positive correlation between SND1 and Nrf2 in glioma according to the results of public databases." (PMID 37202791, 2023). "In our analysis, we further detected the expression patterns of LINC00461 and SND1 among different types of gliomas and the normal brain cortex using the TCGA and GTEX datasets." (PMID 37260771, 2023). "Exogenous expression of miR-184 decreased the proliferation and invasion of glioma cells by regulating SND1 expression." (PMID 38001121, 2023). "SND1, which is highly expressed in glioma, has been reported to function as an m6A “reader” protein to bind and stabilize the m6A-modified RNAs." (PMID 37202791, 2023). "Recently, we found that SND1 serves as a promising malignancy marker and a potential chromatin structure regulator in glioma." (PMID 37885030, 2023). "Our findings elucidate the effect and detailed mechanism of SNAI3-AS1/SND1/Nrf2 signalling axis in ferroptosis, and provide a theoretical support for inducing ferroptosis to improve glioma treatment." (PMID 37202791, 2023). "Our study elucidates the effect and detailed mechanism of SNAI3-AS1/SND1/Nrf2 in ferroptosis, and provides a theoretical support for inducing ferroptosis to improve glioma treatment." (PMID 37202791, 2023). "Using site-directed mutagenesis, we created four predicted N-glycosylation site mutants for SND1 and provided the first evidence that SND1 undergoes N-glycosylation on its Asn50, Asn168, Asn283, and Asn416 residues in human glioma U87 cells." (PMID 36213325, 2022). "SND1 expression in glioma was also observed in immunohistochemistry, and results showed that SND1 was significantly upregulated in clinical glioma samples, especially in GBM." (PMID 36213325, 2022). "Collectively, our results reveal that N-glycosylation at Asn50 is essential for SND1 folding and trafficking, thus essential for the glioma process, providing new insights for SND1 as a potential disease biomarker for glioma." (PMID 36213325, 2022). "In this study, we suggested that all the four potential N-glycosylation sites of SND1 were occupied by the N-glycans in glioma cells using site-directed mutagenesis." (PMID 36213325, 2022). "Clinical and experimental studies also indicate that high expression of SND1 was observed in a spectrum of cancers including glioma, prostate cancer, lung cancer, and liver cancer." (PMID 36213325, 2022).
glioma (continued). "A remarkable mobility shift was noted after treatment, suggesting that N-glycans are ubiquitously present on SND1 in glioma cells." (PMID 36213325, 2022). "Consider the critical role of SND1 in glioma; we firstly detected the presence of N-glycosylation for SND1 in glioma cells." (PMID 36213325, 2022). "Lin Yu demonstrated that SND1 (Staphylococcal nuclease domain-containing protein 1) and RhoA were independent predictors of poor prognosis in glioma patients." (PMID 31339860, 2019). "Mechanistically, we for the first time demonstrated that SND1 and β-catenin were direct functional targets of miR-320a in gliomas, which facilitated our understanding of the mechanisms underlying glioma malignant progression." (PMID 28160566, 2017). "β-catenin is an important glioma promoter, while recent studies have discovered that SND1 promotes oncogenesis and progression through increasing TGFβ1 pathway activity." (PMID 28160566, 2017). "In summary, our study revealed that miR-320a inhibited the proliferation and invasion of glioma cells by directly targeting SND1 and β-catenin, and predicted better prognosis in human gliomas, especially in GBM." (PMID 28160566, 2017). "Contrarily, SND1 and β-catenin expressions were positively correlated with glioma grades and Ki-67 index, but inversely correlated with miR-320a expression and patients’ survival." (PMID 28160566, 2017). "The inverse correlation between miR-320a and SND1 or β-catenin implied that miR-320a downexpression resulted in SND1 and β-catenin overexpressions in gliomas." (PMID 28160566, 2017). "Overexpression (OE) and knock down (KD) studies were performed to unravel the functional significance of SND1 in glioma progression." (PMID 25405367, 2015). "The observation that SND1 regulates several important determinants of glioma progression supports the rationale of using SND1-inhibition as a means of treating glioma patients." (PMID 25405367, 2015). "Knock down of SND1 in malignant glioma cells resulted in a flat-shaped cells, which stained positive with β-galactosidase indicating induction of cellular senescence." (PMID 25405367, 2015). "We hypothesized that this could be a result of the binding ability between LINC00461 and SND1 during the progression of glioma." (PMID 37260771, 2023). "Our study based on the detection of HCR and the functional exploration of this region offers a possibility that LINC00461 and SND1 could act as candidate markers in different types of gliomas." (PMID 37260771, 2023). "SND1 is known to be upregulated in human glioma with a regulatory role in glioma progression." (PMID 38001121, 2023). "The upregulation of SND1 expression significantly correlated with glioma grades and poor prognosis." (PMID 36213325, 2022). "To further determine whether the N-glycosylation-regulated control of SND1 stability has effects on the oncogenicity in glioma, we investigated the cell proliferation and cell metastasis in glioma cells." (PMID 36213325, 2022). "In the current study, we confirmed that SND1 was highly expressed in human glioma." (PMID 36213325, 2022). "In this study, we suggest that SND1 is highly expressed in the glioma." (PMID 36213325, 2022). "In the current study, we provided insights on the functions of N-glycosylated SND1 in glioma." (PMID 36213325, 2022). "However, the upstream mechanisms inducing SND1 and β-catenin overexpressions in gliomas remain poorly understood." (PMID 28160566, 2017). "In this paper, we report for the first time that miR-320a inhibits the proliferation, migration and invasion of glioma cells by directly silencing SND1 and β-catenin, and identify miR-320a and SND1 as independent predictors and β-catenin as an auxiliary predictor for the survival of glioma patients." (PMID 28160566, 2017). "Our previous study showed that MTDH was highly expressed in glioma and could interact with NF-κB component p65 to promote staphylococcal nuclease domain containing 1 (SND1) expression." (PMID 28107197, 2017).
glioma (continued). "Importantly, we found that miR-320a, SND1 and β-catenin, not only were correlated with one another, but also predicted the survival of glioma patients, highlighting their potential values as novel prognostic biomarkers in human gliomas." (PMID 28160566, 2017). "Furthermore, SND1 and β-catenin LIs in gliomas were negatively correlated with miR-320a LI (r = −0.981 or −0.975, P<0.0001) and positively correlated with Ki-67 LI (r=0.984 or 0.975, P<0.0001)." (PMID 28160566, 2017). "Moreover, our previous study showed that MTDH interacted with p65 in the nucleus and promoted SND1 expression in glioma cells." (PMID 28107197, 2017). "We focused on SND1 and β-catenin because they were important glioma promoters." (PMID 28160566, 2017). "Interestingly SND1-KD primary glioma cells demonstrated enhanced sensitivity towards Temozolomide, an FDA approved drug used with radiation therapy as a standard of treatment for GBM patients." (PMID 25405367, 2015). "However, the functional role of N-glycosylation of SND1 in glioma remains to be determined." (PMID 36213325, 2022). "However, the specific contribution of SND1 glycosylation in glioma remains uncertain." (PMID 36213325, 2022). "Furthermore, destabilized SND1 inhibits the glioma cell proliferation and metastasis." (PMID 36213325, 2022). "Herein, we hypothesize that SND1 might play a critical role in the progression of glioma." (PMID 36213325, 2022). "Thus, miR-320a, SND1 and β-catenin could be the novel and clinical feasible candidates for glioma diagnosis and subclassification." (PMID 28160566, 2017). "In our glioma specimens, the expression of Ki-67, a known proliferation marker, not only was significantly increased with glioma grade elevation, but also was inversely correlated with miR-320a expression and positively correlated with SND1 and β-catenin expressions." (PMID 28160566, 2017). "Since miR-320a may also exert anti-glioma effects by silencing other targets and SND1 is a pivotal multifunctional protein promoting oncogenesis and progression, the prognostic significance of β-catenin is not as important as those of miR-320a and SND1 in gliomas." (PMID 28160566, 2017). "Multivariate and univariate analyses ascertained SND1 as an independent predictor and β-catenin as an auxiliary predictor for DFS and OS of glioma patients." (PMID 28160566, 2017). "Kaplan-Meier analyses demonstrated that the high levels of SND1 and β-catenin predicted a short-term DFS (P<0.0001) and OS (P<0.0001) in glioma patients." (PMID 28160566, 2017). "During the preparation of the manuscript, the first evidence for a role of SND1 in STAT3 activation and glioma progression has been reported." (PMID 26323317, 2015). "Moreover, the glioma patients in the same grade, IDH status, age and KPS groups could also be divided into two subgroups with different outcomes based on SND1 and β-catenin expressions, i.e., the higher their expressions were, the poorer prognosis of patients (DFS: P<0.0001; OS: P<0.0001)." (PMID 28160566, 2017).